MIR595 (microRNA 595)
Synonyms: hsa-mir-595; MIRN595
Gene: MicroRNA gene on chromosome 7 (158,532,718 to 158,532,813, reverse strand). Ensembl gene ENSG00000207637.
Diseases named in the same sentence as MIR595 in open-access papers:
MIR595 is named in the same sentence as 2 diseases in open-access papers, as found by Europe PMC text mining. Sharing a sentence is not in itself a finding about the gene and the disease. The quoted sentences say what the papers report.
glioblastoma (1 paper, 2021). The most malignant astrocytic tumor (WHO grade IV). "We found previously uncharacterized miRNA genes in pediatric CNS tumors, including MIR149, MIR214, MIR574 and MIR765, apart from one study that reported MIR595 upregulation in glioblastoma compared to control cells, in vitro." (PMID 34204289, 2021).
CNS tumors (1 paper, 2021). "In cluster 2, MIR149, MIR214, MIR574, MIR595 and MIR765 were globally down-regulated across all CNS tumor samples; ten miRNA genes were also found globally down-regulated in >90% of all samples." (PMID 34204289, 2021).